EZH2 (enhancer of zeste 2 polycomb repressive complex 2 subunit)
Diseases named in the same sentence as EZH2 in open-access papers (continued):
Sharing a sentence is not in itself a finding about the gene and the disease.
ischemic stroke (6 papers, 2013 to 2025). A stroke disorder caused by obstruction of blood flow to the brain, due to thrombotic (local blood clot formation) or embolic (due to a blood clot or other material traveling from another site) event. "In this study, we demonstrated that the EZH2 inhibitor GSK-126 alleviated neuronal apoptosis induced by ischemic stroke." (PMID 35091962, 2022). "The EZH2 inhibitor 3-deazaneplanocin A (DZnep) exerts a neuroprotective effect after ischemic stroke." (PMID 35091962, 2022). "In conclusion, we demonstrated that the EZH2 inhibitor GSK-126 alleviates neuronal apoptosis in ischemic stroke by inhibiting H3K27me3." (PMID 35091962, 2022). "EZH2, a histone methyltransferase, can aggravate neurological deficits following ischemic stroke, while these deficits can be improved by EZH2 inhibitor DZNep." (PMID 34422795, 2021). "Therefore, boosting cholinergic neurotransmission after ischemic stroke likely modulates EZH2 expression/activity in nucleated blood cells, promoting an anti-inflammatory epigenetic program and helping to resolve harmful systemic inflammation." (PMID 40723311, 2025). "Additionally, Smurf2 can enhance neuron differentiation and improve functional recovery from ischemic stroke by ubiquitinating and degrading the EZH2." (PMID 33815059, 2021). "Additionally, in the acute and subacute phases of ischemic stroke, EZH2 may be involved in the reduction in BBB disruption, decreasing neuroinflammation and infarct volume, possibly leading to neuroprotection." (PMID 40723311, 2025). "Targeting EZH2 methyltransferase activity has been proven to be effective in multiple neuroinflammatory diseases, such as neuropathic pain, ischemic stroke and early brain injury (EBI), revealing a cross-talk between EZH2 and TRAF6/NF-κB pathway." (PMID 37391829, 2023). "Moreover, EZH2 may regulate the activation of microglia by activating phosphorylated signal transducer and activator of transcription 3 (STAT3), aggravating the inflammatory response after ischemic stroke." (PMID 35091962, 2022).
liver diseases (6 papers, 2017 to 2023). "Interestingly, a study investigating the sex differences in liver transcription programmes showed that EZH2 also plays a key transcriptional role leading to sex-bias in susceptibility to fibrosis and other liver diseases." (PMID 38504908, 2023). "Here, we used male and female Ezh1/Ezh2 double knockout (E1/E2-KO) mice to address these questions by investigating the requirement of Ezh1 and Ezh2 for sex-biased gene regulation in mouse liver, and to discover any sex-dependent effects of Ezh1/Ezh2 loss on genes associated with liver disease." (PMID 32428001, 2020). "Here, we use an Ezh1-knockout mouse model with a hepatocyte-specific knockout of Ezh2 to investigate the role of H3K27me3 in regulating sex-biased gene expression in mouse liver, and the potential impact of this regulation on sex-biased susceptibility to liver disease." (PMID 32428001, 2020). "As the catalytic subunit of PRC2 complex, EZH2 critically regulates liver homeostasis and shapes the development of liver disorders." (PMID 35256601, 2022). "The histone H3 lysine 27 (H3K27) trimethylating enzyme, enhancer of zeste homolog 2 (EZH2) mediates epigenetic silencing of gene expression and regulates immunity, also involves pathogenesis of several liver diseases." (PMID 29789597, 2018). "In this regard, DZNep-mediated suppression of EZH2 has been reported to enhance lipid accumulation and inflammation in high-fat diet models of rodent liver disease." (PMID 28129116, 2017). "Thus, our findings highlight the potential role of sex differences in histone modifications catalyzed by Ezh1/Ezh2 in widespread sex differences in liver diseases." (PMID 32428001, 2020). "Another histone methyltransferase Enhancer of Zeste Homolog 2 (EZH2), which catalyzes trimethylation of H3K27 (H3K27me3) for transcriptional repression, was shown to play a key role in liver diseases." (PMID 34572442, 2021). "EZH2/H3K27me3 also involves in liver diseases, including nonalcoholic fatty liver diseases, liver fibrosis and hepatitis B12,13." (PMID 29789597, 2018).
liver failure (6 papers, 2018 to 2025). A liver disease characterized by the liver losing or has lost all of its function. "In ALD-related liver failure samples, we found decreased EZH2 and H3K27me3 levels, whose functional consequences is supported by a recent study showing that even a transient PRC2 inhibition is sufficient to trigger irreversible induction of TF encoding genes." (PMID 41385584, 2025). "During the development of liver failure, EZH2 expression significantly increases, and pro-inflammatory cytokines are promoted through the enrichment of H3K27me3 and NF-κB and Akt signaling pathways." (PMID 37781509, 2023). "A study has shown that systemic EZH2-catalyzed H3K27me3 expression increases during liver failure, while its enrichment on the TNFα promoter in Kupffer cells decreases." (PMID 37781509, 2023). "The pathogenesis of liver failure is characterized by a significant increase in EZH2 expression and promotion of pro-inflammatory cytokines through the enrichment of H3K27me3 and NF-κB and Akt signaling pathways." (PMID 37781509, 2023). "The results suggested that EZH2/H3K27me3 promoted the progression of liver failure and that TNF, along with downstream NF-κB and Akt signaling pathways, was manipulated by epigenetic modification with H3K27me3." (PMID 33262329, 2020). "In the present study, EZH2 and H3K27me3 levels were upregulated as liver injury progressed, suggesting that they are involved in liver failure by regulating immune responses." (PMID 33262329, 2020). "This experimental evidence raises the possibility that EZH2 is involved in liver failure by regulating the development and function of DCs." (PMID 33262329, 2020). "During liver failure, the global EZH2-catalysed H3K27me3 increased while its enrichment on Tnf promotor decreased." (PMID 29789597, 2018). "Intrahepatic EZH2+ cells were increased in the liver failure patients, some of them were closely related to CD68+ cells (Kupffer cells), accompanied with substantial increased infiltrating cells, compared to those from HC." (PMID 29789597, 2018). "Significantly more Kupffer cells relating EZH2 and H3K27me3 were detected in the liver failure mice, respectively." (PMID 29789597, 2018). "In conclusion, EZH2 and H3K27me3 contributed to the pathogenesis of liver failure via triggering TNF and other indispensable proinflammatory cytokines." (PMID 29789597, 2018). "EZH2 and H3K27me3 in Kupffer cells from mice liver were increased significantly (P < 0.05) in liver failure mice following LPS/D-GalN injection." (PMID 29789597, 2018). "Collectively, our data suggest that EZH2 enhances some proinflammatory cytokines production upon stimulation during liver failure." (PMID 29789597, 2018). "Overall, our data suggested that EZH2/H3K27me3 promoted the development of liver failure, which was ameliorated using GSK126 via modulation of TNF and overall inflammation." (PMID 29789597, 2018). "At the early phase of liver failure, EZH2/H3K27me3 promote the expression of proinflammatory cytokines, which was via the H3K27me3 enrichment, as well as NF-κB and Akt signalling pathways." (PMID 29789597, 2018). "In the current study, there was a correlation between elevated EZH2/H3K27me3 production and upregulated proinflammatory cytokines during the development of liver failure." (PMID 29789597, 2018). "In the current study, it was investigated the potential role of EZH2/H3K27me3 during the development of liver failure." (PMID 29789597, 2018). "The hepatic EZH2 and H3K27me3 production during liver failure was determined in the liver sections from three ACLF patients, using immunohistochemistry." (PMID 29789597, 2018). "EZH2 inhibitors can relieve the severity of liver failure in mice, which may be related to the reduction in H3K27me3 and the downregulation of liver pro-inflammatory cytokines." (PMID 34276405, 2021).
liver failure (continued). "Compared to directly binding on Tnf promotor as a transcription factor, EZH2 regulated TNF in liver failure might be largely due to its methylation activity and its downstream product (H3K27me3)." (PMID 29789597, 2018). "It invites speculation that EZH2/H3K27me3 is involved in liver failure via regulating immune activation during liver failure." (PMID 29789597, 2018). "Furthermore, inhibitor GSK126 for EZH2-catalysed H3K27me3 ameliorated liver injury and improved survival in liver failure mice, via suppressing TNF and other indispensable proinflammatory cytokines." (PMID 29789597, 2018). "However, the role of EZH2/H3K27me3 in host immunity, particularly in regulating inflammation during liver failure remains to be explored." (PMID 29789597, 2018). "Moreover, the underlying mechanism involved EZH2-catalysed H3K27me3 in the liver failure was explored at molecular level via modification of methyltransferase activity of EZH2 in vivo." (PMID 29789597, 2018). "Furthermore, GSK126 (an inhibitor for EZH2 trimethylation function) was applied in liver failure mice in vivo, and lipopolysaccharide-stimulated mononuclear cells in vitro." (PMID 29789597, 2018). "Interestingly, more than 2-fold Kupffer cells relating EZH2, as well as 3-fold relating H3K27me3, were detected in the liver failure patients, respectively." (PMID 29789597, 2018). "The EZH2 inhibitor GSK126 has been shown to ameliorate liver injury and improve survival in mice with liver failure by inhibiting TNF and other indispensable pro-inflammatory cytokines." (PMID 37781509, 2023). "EZH2 and H3K27me3 were significantly upregulated in human PBMC from liver failure patients or murine Kupffer cells from the liver failure animals, respectively." (PMID 29789597, 2018). "The current study was to determine the role of methyltransferase EZH2 and its catalysed H3K27 trimethylation (H3K27me3) in liver failure, and to further investigate the potential target for liver failure treatment." (PMID 29789597, 2018). "Our data suggest that there was a correlation between increased EZH2/H3K27me3 and upregulated TNF in liver failure." (PMID 29789597, 2018). "Inhibition of EZH2-catalysed H3K27me3 in vivo was carried out using GSK126 to determine the function of EZH2 and H3K27me3 during liver failure in mice model." (PMID 29789597, 2018). "EZH2 and its catalysed H3K27me3 were determined in peripheral blood mononuclear cells (PBMC) from liver failure patients and Kupffer cells from experimental mice." (PMID 29789597, 2018). "Notably, using GSK126 inhibiting EZH2/H3K27me3 directly in vitro significantly reduced TNF in the current study, which raises an interesting question: how do EZH2 and H3K27me3 modulate the proinflammatory cytokines, especially TNF during liver failure." (PMID 29789597, 2018). "Interestingly our data showed that no obvious affinity of EZH2 in Tnf promotor was observed in both normal and liver failure mice." (PMID 29789597, 2018). "Interestingly, no EZH2 recruitment was detected in these four particular regions, which match for the corresponding regions in H3K27me3 from both control and liver failure mice." (PMID 29789597, 2018).
lupus nephritis (6 papers, 2021 to 2024). Glomerulonephritis in the context of systemic lupus erythematosus. "Hyperuricemia and lupus nephritis (LN) are two important causes of CKD, and overexpression of EZH2 and H3K27me3 is detected in those injury kidneys." (PMID 35559246, 2022). "Collectively, in obstructive nephropathy, hyperuricemic nephropathy and lupus nephritis, EZH2 inhibition has a protective effect on the kidney and can delay the progression of the disease." (PMID 35559246, 2022). "Administration of EZH2 inhibitor prolonged the survival, reduced the levels of anti-dsDNA autoantibodies, and improved lupus nephritis of the mice." (PMID 33868295, 2021). "We verified the therapeutic effects of EZH2 inhibitor on lupus nephritis in NZB/NZW F1 mice, which depends on IFN-I signaling pathway for disease progression." (PMID 33868295, 2021). "We found EZH2 was upregulated in renal biopsies from lupus nephritis patients as compared with normal para-carcinoma kidney tissues; and there were significant positive correlations between the expression of EZH2 and CXCL10 or IFIT3, respectively." (PMID 33868295, 2021). "We prove that EZH2 inhibitor can inhibit the in vivo activation of IFN-I signaling pathway and mitigate lupus nephritis in mouse model." (PMID 33868295, 2021). "Here, we investigated the role of EZH2 in IFN-I signaling pathway and the therapeutic effects of EZH2 inhibitor on lupus nephritis in NZB/NZW F1 mice, a model depends on IFN-I, which differs from MRL/lpr mice." (PMID 33868295, 2021). "EZH2 inhibitor has the potential to inhibit IFN-I signaling pathway and alleviate lupus nephritis." (PMID 33868295, 2021).
non-alcoholic fatty liver disease (6 papers, 2015 to 2024). "In terms of lipid accumulation, long non-coding RNA maternally expressed gene 3 (LncRNA MEG3) up-regulates Sirt6 by ubiquitinating enhancer of zeste homolog 2 (EZH2), which suppresses lipid accumulation and inflammation in vitro and alleviates nonalcoholic fatty liver disease in vivo." (PMID 39372420, 2024). "To properly correlate the hepatic modulation of EZH2 expression upon short/long HFD consumption, we established a well-described in vitro model of non-alcoholic fatty liver disease (NAFLD) using immortalized HUH-7 cells challenged with PA (24 h, 100 μM) and EPZ-6438 (24 h, 3.3 μM)." (PMID 39408226, 2024).
periodontitis (6 papers, 2021 to 2025). An acute or chronic inflammatory process that affects the tissues that surround and support the teeth. "EZH2 encodes for a methyltransferase enzyme that is involved in osteoclast regulation and is proposed as a target for periodontitis." (PMID 35132337, 2022). "This study is aimed at determining the potential role and underlying mechanism of EZH2 in periodontitis." (PMID 34899921, 2021). "However, little information is available regarding the underlying mechanism of EZH2 in periodontitis." (PMID 34899921, 2021). "TFs, such as Ezh2 and Suz12, activated in periodontitis, provide additional mechanistic insights." (PMID 40076622, 2025). "For instance, in our PPI network we found that Smad ubiquitination regulatory factor-2 (SMURF2), an ubiquitin E3 ligase responsible for proteasome-mediated degradation of enhancer of zeste homolog 2 EZH2 which is a process required for neuron differentiation is present in periodontitis." (PMID 34065604, 2021). "Modulation of the NF-κB pathway through the inhibition of EZH2 may offer a new perspective on the treatment of chronic apical periodontitis." (PMID 34899921, 2021). "In addition, we preliminarily evaluated methyltransferase molecule EZH2 in periodontitis, and examined its role in PDLSCs, PDLSCs+LPS, PDLSCs+LPS+GSK126." (PMID 34347624, 2021). "Gene correlation analysis demonstrated that EZH2 gene was highly positively correlated with DNMT1 and DNMT3N in periodontitis samples (FDR<0.01)." (PMID 34347624, 2021).
primary myelofibrosis (6 papers, 2016 to 2025). Myelofibrosis with myeloid metaplasia is a myeloproliferative disease with annual incidence of approximately 1 case per 100,000 individuals and age at diagnosis around 60 (an increased prevalence is noted in Ashkenazi Jews). "Overall, MPN patients, particularly primary myelofibrosis (PMF) patients, and patients with MDS, MDS/MPN or (secondary) AML who carry EZH2 mutations have a worse prognosis compared to patients with wild-type EZH2." (PMID 32650416, 2020). "Gene mutations in epigenetic regulators (ASXL1, TET2, DNMT3A and EZH2) and RNA splicing (U2AF1 and SRSF2) were considered as the additional subclonal mutations and cooperated with the MPN driver mutation (JAK2, MPL or CALR) to play a key role in the pathogenesis of primary myelofibrosis." (PMID 35740649, 2022).
pulmonary arterial hypertension (6 papers, 2012 to 2025). Pulmonary arterial hypertension (PAH) is a group of diseases characterized by mean pulmonary artery pressure >20 mmHg and elevated pulmonary arterial resistance leading to right heart failure. "Increased EZH2 activity inhibits SOD1 expression leading to ROS accumulation that contributes to the progression of pulmonary artery hypertension." (PMID 38580969, 2024). "Omura used CMs from rats with pulmonary hypertension to demonstrate that H19 silencing upregulates the histone methyltransferases, enhancer of Zeste homolog 2 (EZH2) and E2F1." (PMID 36188624, 2022). "Elevated EZH2 levels in pulmonary arterial hypertension (PAH) patients can be targeted with GSK126, demonstrating decreased PASMC proliferation and improved mitochondrial function in vitro." (PMID 39981435, 2025).
rheumatoid arthritis (6 papers, 2014 to 2026). A chronic, systemic autoimmune disorder characterized by inflammation in the synovial membranes and articular surfaces. "In rheumatoid arthritis, decreased EZH2 expression in circulating CD4+ T cells has been linked to impaired Treg differentiation." (PMID 41518566, 2026). "Comparable findings have been reported in rheumatoid arthritis, where EZH2 downregulation has been reported in naïve CD4 T cells, indicating that epigenetic abnormalities in immune cells may be an early event in chronic inflammatory diseases." (PMID 41518566, 2026). "From a recent clinical study, it was found that T cells from Rheumatoid arthritis (RA) patients exhibited lower Ezh2, which regulated T cell differentiation through promoting epigenetic modification." (PMID 32709019, 2020). "In rheumatoid arthritis (RA), IL17 in synovial fluid may be involved in the downregulation of EZH2 in CD4+ T cells, implying that enhanced TH17 differentiation may impair the function of the CD30+ Treg subset." (PMID 39170389, 2024).